MTOR (mechanistic target of rapamycin kinase)
Diseases named in the same sentence as MTOR in open-access papers (continued):
Sharing a sentence is not in itself a finding about the gene and the disease.
hematological cancers (15 papers, 2012 to 2026). "The goal of this study was to explore the role of Akt/mTOR independent progranulin related signaling pathway in regulation to the proliferation of hematopoietic cancer cells." (PMID 33490663, 2021). "Accordingly, pharmacologic antagonists of mTOR are anticipated to be effective against many types of solid tumors and hematologic cancers." (PMID 22607709, 2012). "Subsequently, the combination of glutamine degradation and mTOR inhibition demonstrates robust cytotoxicity in PI3K-driven solid and hematological tumors in pre-clinical and clinical settings." (PMID 40038309, 2025). "In summary, this is the first report demonstrating that progranulin depletion inhibits proliferation of hematopoietic cancer cells through TGF-β production and inhibition of Akt/mTOR pathway." (PMID 33490663, 2021). "CX-4945 exerts anti-proliferative effects in hematological tumors by downregulating CK2 expression and suppressing activation of CK2-mediated PI3K/Akt/mTOR signaling pathways." (PMID 25873900, 2015). "Since the identified association of the poor prognosis and chemoresistance in AMLs with the PI3K/Akt/mTOR activation, we herein investigated the antiproliferative activity of FD268 against five hematological cancer cell lines: HL-60, MOLM-16, Mv-4-11, KG-1 and EOL-1." (PMID 36413544, 2022). "Taken together, these results suggest that the role of Akt/mTOR and ERK pathways in progranulin related signal transduction is still important in hematopoietic cancer cells, and progranulin is one of the attractive targets to suppress both pathways simultaneously." (PMID 33490663, 2021). "mTOR plays a central role in AML and a broader spectrum of hematological cancers." (PMID 33828590, 2021). "We describe a kinase-independent function of CDK8 in hematopoietic tumors and suggest that the proteasome-induced degradation of CDK8 in combination with inhibition of mTOR might represent an addition to the therapeutic armory." (PMID 31628323, 2019).
mitochondrial disease (15 papers, 2015 to 2023). "Several studies have indicated that genetic or pharmacological inhibition of mTOR can rescue defects associated with severe mitochondrial disease in yeast, worms, fruit flies, and mice." (PMID 28919908, 2017). "In response to preclinical data from the Ndufs4(KO) mouse (detailed below), mechanistic target of rapamycin (mTOR) inhibitors have also recently been tested in small cohorts of mitochondrial disease patients." (PMID 36056365, 2022). "Taken with prior studies probing the benefits of mTOR inhibitors in mitochondrial disease, these data provide strong evidence that the pathogenesis of LS is immune mediated." (PMID 36056365, 2022). "It was these findings that paved the way for the use of mTOR inhibitors as potential therapies for mitochondrial disease." (PMID 34456746, 2021). "Intervention strategies such as those targeting NAD + metabolism, or mTOR inhibition have alleviated mitochondrial disease in some models of LS and related mitochondrial disorders." (PMID 34456746, 2021). "Recent studies have already shown that kinase inhibition can alleviate mitochondrial dysfunction in mouse models of mitochondrial disease by dampening mTOR, PKC, or AMPK signaling." (PMID 34144036, 2021). "Clinical data has reported mTOR signalling as a mechanism that connects mitochondrial disease to gliosis, with both in vitro, and in vivo, studies showing that gliosis can be induced by targeted disruptions to mTOR signalling." (PMID 34639097, 2021). "Taken together, these results show tissue-specific regulation of the mTOR signalling pathway in mitochondrial disease that depends on the energy requirements of individual tissues." (PMID 32130224, 2020). "The mTOR inhibitor rapamycin ameliorates the clinical and biochemical phenotype of mouse, worm, and cellular models of mitochondrial disease, via an unclear mechanism." (PMID 30309855, 2018). "Our data perfectly complement with recent data provided by Kaeberlein and colleagues who demonstrated a convincing beneficial effect of mTOR inhibition in a rare mitochondrial disease with mainly neurological symptoms." (PMID 25643582, 2015). "Importantly, mTOR activity was found to be hyperactive, and rapamycin rescued grip strength and metabolic defects, supporting a role for mTOR in mitochondrial disease beyond Ndufs4(KO)." (PMID 36056365, 2022). "While this study focused on the impact of S6K1 and mTOR signaling in severe mitochondrial disease, these results may have relevance to normative aging as well." (PMID 28919908, 2017). "To assess whether S6K1 plays a role downstream of mTOR in mediating mitochondrial disease progression, we crossed whole body and tissue-specific S6K1 knockout mice into the NKO background and examined the impact on health and survival." (PMID 28919908, 2017). "Our in vivo data are consistent with reports in haematopoietic stem cells in which mTORC1 activity increases mitochondrial biogenesis, contributing to ROS‐dependent decreased stemness and haematopoiesis, and that mTOR inhibition can alleviate mitochondrial disease." (PMID 26848154, 2016). "Taken together, these data indicate that decreased S6K1 activity in liver is sufficient to delay the neurological and survival defects caused by deficiency of Complex I and suggest that mTOR signaling can modulate mitochondrial disease and metabolism via cell non-autonomous mechanisms." (PMID 28919908, 2017). "In this study, we found that inactivation of the mTOR substrate S6K1 in the whole body modestly enhances survival and delays the onset of a characteristic neurological symptom in the NKO mouse model of severe mitochondrial disease resulting from Complex I deficiency." (PMID 28919908, 2017). "In summary, we show here that whole body disruption or liver specific disruption of the mTOR substrate S6K1 can increase survival and delay disease symptoms in a mouse model of severe mitochondrial disease." (PMID 28919908, 2017).
mitochondrial disease (continued). "We have previously reported that high dose rapamycin treatment is sufficient to delay mitochondrial disease in the NKO mice and suppress disease phenotypes including neurodegeneration, hyperactivation of mTOR, and low body fat." (PMID 28919908, 2017).
CNS tumors (11 papers, 2016 to 2025). "Inhibition of the mammalian target of rapamycin (mTOR) signaling pathway remains another therapeutic target for CNS tumors." (PMID 40422539, 2025). "Considering that others have shown a synergistic effect between ULKi inhibition and mTOR inhibition, additional studies will be important to determine if we could increase treatment efficacy using mTOR inhibitors in combination with these early stage autophagy inhibitors in CNS tumors." (PMID 32457939, 2020). "As with studies showing synergy between ULK1 and VPS34 inhibitors with mTOR inhibition, our data would support the increased efficacy of autophagy inhibition via ULK1 and VPS34 in CNS tumor cells under stressed conditions." (PMID 31515514, 2019). "IFNγ-mediated induction of IDO1 was strongly reduced by mTOR inhibition with rapamycin suggesting that functional relationship between mTOR and IDO1 might be specific of MB among CNS tumors." (PMID 27174915, 2016).
blood cancers (9 papers, 2014 to 2022). "Interestingly, a recent study in human blood neoplasms has also found GNAO1 mutations to activate AKT/ERK/mTOR signaling." (PMID 36003298, 2022). "GNB1 mutations have been found in different hematological neoplasm cell lines and are thought to increase the activation of AKT/ERK/mTOR signaling." (PMID 36003298, 2022). "In blood cancers mTOR signaling pathway is commonly activated to promote uncontrolled cellular growth and proliferation." (PMID 25243120, 2014). "Our studies provide a clinical rationale of use mTOR inhibitors and chaperone protein inhibitors in combination regimens for the treatment of human blood cancers." (PMID 25243120, 2014). "Despite showing promising clinical efficacy in some blood cancers, PI3K/mTOR inhibitors lack single-agent cytotoxicity in aggressive diseases like DLBCL." (PMID 26460954, 2015). "Our data suggest that reduced 4EBP expression might be a biomarker of resistance to asTORi and to dual PI3K/mTOR inhibitors in DLBCL and other blood cancers." (PMID 24586420, 2014).
vasculopathy (8 papers, 2011 to 2025). "In kidney transplant patients with APS, mTOR inhibitors prevent the recurrence of vasculopathy and, consequently, graft loss." (PMID 40141392, 2025). "Besides, aPLs may induce upregulation of the mechanistic target of rapamycin (mTOR) complex on endothelial cells, which is associated with vasculopathy." (PMID 37275894, 2023). "Another effect of EC activation is triggering the pathogenic cascade towards vasculopathy, through the successive involvement of phosphatidylinositol 3-kinase (PI3K)-AKT and mammalian target of rapamycin (mTOR) pathways." (PMID 39457063, 2024). "For this reason, it might be suggested that vitamin K antagonist treatment be supplemented with an mTOR inhibitor, which would block vasculopathy and reduce the recurrence of APS leg ulcers or further complications." (PMID 40141392, 2025). "In addition, by combining clinical studies with in vitro experiments, it has been shown that mTORC plays a role in the development of APS vasculopathy, with mTOR inhibitors able to reduce vascular proliferation in APS nephropathy." (PMID 37511365, 2023). "The mTOR signaling plays an important role in the pathomechanism of HLA antibody-mediated endothelial cell activation and proliferation, which lead to rejection and vasculopathies." (PMID 38993866, 2023). "In addition, mTOR inhibitors have been reported to improve vasculopathy in cardiac transplantation patients." (PMID 30473931, 2018). "aPLs activate mTOR via the PI3K-AKT signaling pathway, significantly contributing to the development of vasculopathy observed in APS nephropathy." (PMID 40141392, 2025).
retinopathy (7 papers, 2019 to 2025). "We have previously engineered an AAV2 vector encoding shmTOR,15 which precisely targets and silences the mTOR gene, thereby diminishing the heightened mTOR signaling seen in various retinopathy models in animals." (PMID 39897639, 2025). "Lee and colleagues demonstrate that AAV2-shmTOR alleviates hypoxia-induced inflammation in retinopathies by downregulating mTOR signaling, reducing CCL3 secretion in Müller cells, and limiting CCR5-positive microglia." (PMID 39897639, 2025). "Dysregulation of the mTOR signaling pathway is frequently observed in several forms of retinopathy, including DR and AMD." (PMID 39897639, 2025). "Next, we examined in a rat model of oxygen-induced retinopathy (OIR) the therapeutic potential of the mTOR-inhibiting virus vector versus various angiogenic retinal disorders, including retinopathy of prematurity and DR." (PMID 35709240, 2022). "Here, we confirmed that dietary supplementation with SkQ1 starting at the age of 1.5 months suppresses the development of the AMD-like retinopathy in old OXYS rats, and for the first time, showed that its effects are associated with a decrease in the accumulation of Aβ and in mTOR activity." (PMID 31208023, 2019). "This study provides evidence that in hypoxic retinal disorders, AAV2-shmTOR-mediated inhibition of the mTOR pathway reduces activated microglial cell activity via Müller cells, leading to diminished inflammatory pathologies." (PMID 39897639, 2025). "In mice with oxygen-induced retinopathy, modeling aberrant retinal vascular development, targeting mTOR activity through either rapamycin or VEGF-mediated signaling revealed that, in endothelial cells, the mTOR pathway is activated by VEGF." (PMID 34215725, 2021). "Blocking mTOR signalling can reverse shunts in mice lacking BMP9/10 and in Endoglin mutant zebrafish, like vascular malformations in mice with overactivated PI3 kinase signalling or in a model of oxygen induced retinopathy." (PMID 39656297, 2024).
endocrine diseases (6 papers, 2015 to 2021). "Thus, it can be assumed that the mTOR pathway participates in the development of PCOS, a common endocrinopathy disease involving both reproduction and metabolism." (PMID 33947426, 2021).
gynecologic tumors (6 papers, 2011 to 2026). "Conversely, studies in gynecological tumors and gastrointestinal cancers were more enriched in studies evaluating PTEN and protein markers of “mTOR or AKT activation”; and these were linked with worse outcome." (PMID 24777052, 2014). "We evaluated lineage-specific drug sensitivity in gynecologic tumors and discovered that EOCs demonstrated enhanced sensitivities to multiple EGFR inhibitors, while ECs were particularly sensitive to everolimus, an mTOR inhibitor." (PMID 31771620, 2019).
peripheral neuropathy (6 papers, 2022 to 2024). A disorder affecting the peripheral nervous system. "Yin demonstrated that Astragaloside IV promotes autophagy and mitigates peripheral neuropathy by regulating the PI3K/Akt/mTOR signaling pathway through miR-155." (PMID 39338303, 2024). "Furthermore, mTOR hyperactivation can be observed in diabetic patients with small fibre neuropathy, a condition where it can be argued that a regenerative deficit is present." (PMID 36362354, 2022).
central nervous system diseases (5 papers, 2017 to 2024). "Rapamycin (RAPA) can activate autophagy by inhibiting the mTOR pathway and has exhibited promising effects in treating central nervous system disorders; however, its limited ability to cross the blood-brain barrier (BBB) has hindered its clinical efficacy, leading to substantial side effects." (PMID 39113803, 2024). "mTOR signal pathway plays an important role in central nervous system diseases." (PMID 28177899, 2017).
intestinal diseases (5 papers, 2015 to 2025). "This not only provides experimental evidence for elucidating the role of the mTOR pathway in the pathogenesis of intestinal diseases but also offers diverse ideas for developing natural drug intervention strategies targeting mTOR." (PMID 41480384, 2025). "In conclusion, we report that TSC2/mTOR signaling regulates intestinal cell differentiation in a Notch-dependent manner, thus providing a better mechanistic understanding of mTOR inhibition and its potential beneficial effects in certain intestinal diseases." (PMID 25654764, 2015).
skeletal diseases (5 papers, 2015 to 2024). "In the past few years, mTOR emerged as an important regulator of skeletal development, growth, and homeostasis; the dysregulation of its activity contributes to the development of several skeletal diseases, both chronic and genetic." (PMID 34122519, 2021). "We speculate that targeting mTOR signaling may be a valuable approach for treating skeletal diseases." (PMID 29423330, 2018). "We recently demonstrated that parathyroid hormone (PTH)/PTH-related peptide (PTHrP) control the levels of DEPTOR, an inhibitor of the mechanistic target of rapamycin (mTOR), and that DEPTOR levels are altered in different skeletal diseases." (PMID 36726589, 2022).
extrapyramidal movement disorders (3 papers, 2022 to 2024). "An increasing number of studies have linked extrapyramidal movement disorders to excessive activation of the mTOR signaling pathway in MSNs that leads to both upregulated protein biosynthesis and suppression of autophagy that causes accumulation of toxic proteins." (PMID 35013125, 2022). "Metformin can inactivate mTOR and decrease mTOR signaling, reducing age-related pathologies, including movement disorders and insulin insensitivity." (PMID 38333746, 2024). "Similarly, upregulated proteins in HD neurons were related to pathways and diseases involved in axon guidance, autophagy, mTOR, and neurodegeneration, including movement diseases and HD." (PMID 39174523, 2024). "With the existing studies, we postulated that sustained activation of the mTOR/S6K axis and suppressed autophagy may lead to excessive protein synthesis and toxic protein accumulation in the striatum, which may contribute to extrapyramidal movement disorders." (PMID 35013125, 2022). "In contrast, depletion of the striatal mTOR gene abrogated D2R-mediated motor effects without altering D1R-mediated movement disorders in mice." (PMID 35013125, 2022). "However, haloperidol failed to trigger extrapyramidal movement disorders in the mTOR-depleted mice." (PMID 35013125, 2022).
gynecological diseases (3 papers, 2019 to 2024). "Pharmacological agents such as rapamycin, an mTOR inhibitor that enhances autophagy, or chloroquine/hydroxychloroquine, which inhibit autophagy, have been explored as potential treatments in similar gynecological diseases." (PMID 39768424, 2024).
musculoskeletal diseases (3 papers, 2019 to 2025). "Hence, the DEMs may participate in regulating chondrogenic differentiation and chondrocyte functionality, and they may potentially prevent cartilage loss in musculoskeletal diseases via mediating mTOR signaling transduction." (PMID 36230915, 2022). "In terms of demonstration of mTOR levels in fracture patients, this pathway has been investigated in terms of musculoskeletal disorders after abruptly leaving the mTOR pathway." (PMID 31655537, 2019).
gastrointestinal disorders (2 papers, 2021 to 2024). "In addition, extensive research has shown the contribution of PI3K/Akt/mTOR signaling cascades in gastrointestinal disorders." (PMID 38649659, 2024).
neoplastic disorders (2 papers, 2023 to 2024). "Since the dysregulation of the mTOR pathway is implicated in several diseases (in particular neoplastic disorders), mTOR inhibitors, such as rapamycin and rapamycin analogs (rapalogs), exhibit a number of useful actions." (PMID 37759601, 2023). "mTOR has been the focus of previous research in the field of neoplastic disorders in several studies." (PMID 39261960, 2024).
gastrointestinal disease (1 paper, 2026). A disease that occurs in the gastrointestinal system, excluding the hepatobiliary system. "By integrating the latest research findings, we systematically elaborate on how metformin exerts therapeutic effects on gastrointestinal diseases through the AMPK/mTOR pathway and the effects of combination therapies." (PMID 41736859, 2026).
neuromuscular disease (1 paper, 2014). "The increase of KBs concentration, the reduction of blood glucose together with the involvement of many important pathways (e.g., IGF-1/AKT/mTor, AMPK/PGC1α) has shown to be a potential therapeutic weapon against many neurological and neuromuscular diseases." (PMID 25101284, 2014).
overlap syndrome (1 paper, 2018). "We therefore aimed, in our current study, to investigate the role of the mTOR pathway in the pathologic changes observed in minor salivary gland biopsies (MSGBs) from SS, SSc, and SS/SSc overlap syndrome patients." (PMID 30075746, 2018). "Our current findings suggest that the mTOR pathway might play an active role in the pathology of SS, SSc, and overlap syndrome." (PMID 30075746, 2018).
skeletal dysplasia (1 paper, 2025). Any Mendelian diseases that affects growth and development of the skeleton. "A homozygous mutation in the catalytic domain of SIK3 (Arg187Cys, rs1565460853) impairs SIK3 activity and leads to skeletal dysplasia by altering mTOR activity downstream of the PTH/PTH-related protein signaling during skeletogenesis." (PMID 40384110, 2025). "In 2018, Csukasi and colleagues reported a new skeletal dysplasia caused by a homozygous mutation in the catalytic domain of SIK3 (Arg187Cys) and observed decreased activity of mTORC1 and mTORC2 due to accumulation of DEPTOR, a negative regulator of both mTOR complexes." (PMID 40384110, 2025).